EGF (epidermal growth factor)
Diseases named in the same sentence as EGF in open-access papers (continued):
Sharing a sentence is not in itself a finding about the gene and the disease.
cancer (continued). "Targeting EGF can inhibit the growth of cancer cells overexpressing EGFR." (PMID 40859900, 2025). "The presence of EGF allowed the nanoparticles to interact strongly with cancer cells that expressed EGFR, as the cancer cells could take up the cells via EGF receptor-mediated endocytosis." (PMID 40650240, 2025). "The potential therapeutic benefits of EGF must be weighed against its theoretical pro-carcinogenic effects, although there is no clear evidence suggesting that topical EGF increases cancer risk." (PMID 39924511, 2025). "Thus, in both cancer and non-cancer models, EGF regulates several amino acids critical for RPE and retinal function, but its effects in the RPE itself remain poorly defined." (PMID 39433211, 2025). "In vitro and in vivo studies show that macrophages enhance cancer cell invasion and migration by releasing cytokines and chemokines regulated by EGF and CCL18 or by remodeling the extracellular matrix through protease activity, increasing chemoattractant availability." (PMID 40692603, 2025). "However, to directly use EGF-NPs as novel anti-cancer agents, their unique cytotoxicity via signal condensation needs to be investigated using polymeric platforms." (PMID 41140511, 2025). "Indeed, the gene ontology analysis also showed many groups highly related to cancer hallmarks, such as angiogenesis, growth factor signalling by EGF and PDGF and cell cycle." (PMID 39508147, 2025). "In addition, the secretion of growth factors, such as TGF-β and epidermal growth factor (EGF), can potentiate cancer cell proliferation and make them less susceptible to programmed cell death." (PMID 40362529, 2025). "However, when EGF is immobilized on gold NPs, its effect on cancer cells changes from promoting proliferation to inducing apoptosis." (PMID 41140511, 2025). "Taken together, our findings highlight the relevance of CCL18 and EGF in cancer biology and underscore their potential as biomarkers, where their expression changes may have diagnostic and therapeutic implications." (PMID 40692603, 2025). "Overall, this study highlights EGF-NP conjugates as novel anti-cancer drugs." (PMID 41140511, 2025). "Moreover, CAPS seems to play a role in stimulating the proliferation of cancer cells through the modulation of the cited pathways in which CAPS is involved or downregulating cell differentiation following the stimulus of the epidermal growth factor." (PMID 40729375, 2025). "Importantly, several pathways, such as the TGF-β and EGF/EGFR signaling pathways, which are closely associated with cancer progression and metastasis, were found to be highly enriched with ADSCs-EVs treatment." (PMID 39759123, 2025). "Furthermore, EGF nanoparticles exhibited high cytotoxicity against cancer cells responding poorly to conventional EGFR-targeted anti-cancer drugs, showing potential for future medical applications." (PMID 41140511, 2025). "Additionally, epidermal growth factor (EGF) signalling between the cancer cells and the TAMs increased metabolic activity, potentially contributing to chemoresistance." (PMID 40806629, 2025). "The epidermal growth factor (EGF) has a well-established role in cellular proliferation, with aberrant expression and/or activating mutations of the EGF receptor (EGFR) linked to the development of several cancers." (PMID 39924511, 2025). "Ingenuity pathway analysis (IPA) detected downregulation of many canonical pathways related to growth and cancer, including Wnt/β‐catenin, EGF signalling, TGF‐β signalling as well as repression of inflammatory pathways such as TNFR1 signalling, TNFR2 signalling and IL‐6 signalling." (PMID 39508147, 2025). "Therefore, in this study, we aimed to investigate the anti-cancer activities of EGF-conjugates with two kinds of polymeric nanoparticles: polystyrene nanoparticles and polymeric micelles." (PMID 41140511, 2025).
cancer (continued). "Some theories propose that malignant tumours release growth-promoting factors, such as platelet-derived growth factor and epidermal growth factor, or that they secrete hormones stimulating melanocyte-stimulating hormones, leading to increased growth of melanocytes, fibroblasts, and keratinocytes." (PMID 40142228, 2025). "While EGF survival signalling in NSCs has been less studied, it is well-characterized in cancers." (PMID 40593476, 2025). "EGF has similar lipogenesis-promoting effects in most non-cancer cells." (PMID 39433211, 2025). "Specifically, EGF may activate various signaling pathways that contribute to cellular growth, invasion, and the overall progression of cancer." (PMID 40656954, 2025). "Interestingly, TGF-β has been shown to work synergistically with EGF in promoting cancer invasion and metastasis." (PMID 40362536, 2025). "Finally, as C-MYC up-regulation is amplified by EGFR signaling in murine models of CRC, the combined use of ULD of TGF-β, EGF, and SNA-MYC in 2LC1 is intended to downregulate their associated pathways, counteracting the uncontrolled cancer cell proliferation." (PMID 40362536, 2025). "EGF, acting through the EGF receptor, promotes cancer development." (PMID 38779086, 2024). "In addition, there is an interactive relationship among EGF, growth factor, metallothionein 2A, and MMPs in malignant tumors." (PMID 38374934, 2024). "The inhibition of EGFR expression in cancer cells could inhibit the epidermal growth factor that induces increased proliferation, migration, and apoptosis." (PMID 38338029, 2024). "Finally, we examined the role of phosphorylation of FilGAP in chemotactic cancer cell invasion against EGF gradient." (PMID 38426123, 2024). "With EGF/EGFR hypo‐methylation accelerating cancer growth by activating EGFR pathway." (PMID 39036344, 2024). "In any case, downstream of EGF, phosphorylation of Ser621/Ser625 is important for the regulation of FilGAP localization to the actin cytoskeleton, which may be important for cancer cell chemotaxis." (PMID 38426123, 2024). "The most significantly enriched pathways of HSPcluster-B are associated with cancer and inflammatory responses, including type II interferon to JAK-STAT signaling pathway, IL10 family to JAK-STAT signaling pathway, EGF EGFR PI3K NFKB signaling pathway, and TNF NFKB signaling pathway." (PMID 39430254, 2024). "Finally, we showed that nonphosphorylatable FilGAP mutant strongly suppresses the chemotactic cancer cell invasion toward EGF gradient." (PMID 38426123, 2024). "Indeed, LINC00265 has been shown to promote cell proliferation and viability in a number of cancers by interacting with other non-coding RNAs and key signaling pathways such as Epidermal Growth Factor (EGF) and Wnt/β-catenin." (PMID 38948024, 2024). "Salama developed a complex of TiO2NPs ligated through polyethylene glycol to EGF (epidermal growth factor), increasing the selectivity of NPs to cancer cells that expressed EGFR (epidermal growth factor receptor) and increasing PDT efficiency on A431 epidermal cancer cells." (PMID 39065629, 2024). "Finally, we have revealed that phosphorylation of FilGAP is required for efficient cancer cell chemotaxis toward the EGF gradient." (PMID 38426123, 2024). "Considerably, more cancer cell lines and animal model will need to be done to better characterize the precise action mechanism and the signalling pathways involved therapeutic potential benefits of PL molecular mechanisms, especially in the EGF pathway." (PMID 38635559, 2024). "ZN444B-treated cancer cells were unable to respond to the EGF stimulus to migrate and invade." (PMID 39010083, 2024). "The PDO media utilized in this study contain human EGF, and it is therefore possible that excessive EGFR signaling due to the combination of a Kras mutation and additional EGFR activation by EGF in the media leads to cancer cell apoptosis." (PMID 38542253, 2024).
cancer (continued). "RNF144A maintains EGFR signaling to encourage cancer cell proliferation that is dependent on EGF." (PMID 38313020, 2024). "Moreover, considering the potential interplay between HGF and EGF in activating signal transduction pathways that promote cancer cell proliferation, we are also examining possible variations in blood EGF levels among patients with type 2 DM." (PMID 38654922, 2024). "It is possible that supplements such as epidermal growth factor (EGF) in our culture medium may substitute for oncogenic KRAS to induce pre-cancer signatures in organoid culture." (PMID 38280869, 2024). "EGF stimulates EGFR to increase the production of IL-8 from cancer cells." (PMID 38673992, 2024). "The released epidermal growth factor (EGF), in response, stimulates cancer proliferation." (PMID 38787372, 2024). "Repeated FRAP of CapG in the cell nucleus is a suitable functional assay to assess downstream effects of signaling cascades in the single living cancer cell and demonstrated that CapG’s nuclear shuttling increased within minutes after EGF stimulation and depends on the phosphorylation of serine S70." (PMID 39369027, 2024). "Epidermal growth factor (EGF) is a protein involved in cell proliferation and survival, and it’s over activity has been linked to the development and progression of several types of cancer." (PMID 38635559, 2024). "The active targeting strategy of nanoparticles is mainly focused on the overexpression of many receptors such as epidermal growth factor, folate, transferrin, and integrin receptor present on the surface of vascular endothelial cells of cancer cells or tumors compared to normal cells." (PMID 39319107, 2024). "A human epidermal growth factor erbB-2, also known as Her-2, triggers cell invasive ability, and a high level of Her-2 could promote cancer cell growth, invasive ability, and resistance to chemotherapy drugs in ER-positive cells." (PMID 37957856, 2024). "EGF regulates the motility, adhesion, and metastasis of cancer cells." (PMID 39590368, 2024). "The combination of CIMAvax-EGF with TKIs or ICIs might further facilitate the transformation of advanced cancer into a chronic disease." (PMID 39766327, 2024). "Indeed, GBM has the highest frequency of alterations in the EGF/EGFR pathway across 33 types of human cancer." (PMID 39606019, 2024). "Notably, no survival differences were seen in individuals with distinct ECOG performance status, different cancer histology, and EGF concentrations above or below 870 pg/ml." (PMID 38304035, 2023). "Our results suggest that mechanical activation via Piezo1, Src, and p38 may be more relevant to controlling repair, regeneration, and cancer growth than tyrosine kinase signaling via canonical EGF signaling, suggesting an alternative therapeutic approach." (PMID 37756411, 2023). "Coupling of EGF/EGFR to Akt by IQGAP1 has implications in cancer." (PMID 37071417, 2023). "EGF is a common factor involved in cell motility processes, such as cancer metastasis." (PMID 37894950, 2023). "The combined data showed that GFP-EGF could play the role of natural EGF in cancer cells by mediating the phosphorylation of EGFR." (PMID 36611158, 2023). "Thus, the signaling pathway of EGF-induced cancer progression is parallel with the ER-driven cancer progression." (PMID 37681860, 2023). "EGF-regulated MAPK/ERK signal cascade to induce cancer cell survival and proliferation." (PMID 37372974, 2023). "In addition to the typical activation of EP receptors, PGE2 has been shown to promote cancer progression through interaction with carcinogenic signals, including epidermal growth factor (EGF) and its receptor (EGFR)." (PMID 37138287, 2023). "These include epidermal growth factor (EGF), fibroblast growth factor (FGF), vascular endothelial growth factor (VEGF), and hepatocyte growth factor (HGF), each of which has been implicated in the malignant progression of various cancer types." (PMID 38067195, 2023).
cancer (continued). "By understanding the different t actions of FGF1 and EGF on individual cancer cell types, targeted approaches should become possible to develop new effective treatment approaches while preventing the acquisition of drug resistance and cancer progression." (PMID 37509496, 2023). "Epidermal growth factors (EGF) secreted by fibroblasts can boost the size of spheroids by upregulating the α5 integrin expression on the surface of MICs enabling the recruitment and adhesion of these cancer cells to the floating cell masses." (PMID 38132318, 2023). "In addition, the proliferation effect of cancer cells, mediated by epidermal growth factor (EGF), is also inhibited by TsIIA." (PMID 36798821, 2023). "Additionally, TAMs can secrete factors like the epidermal growth factor (EGF), which can trigger survival pathways in cancer cells, rendering them resistant to anti-EGFR drugs." (PMID 37760801, 2023). "In fact, EGF is a well-known contributor to cancer progression." (PMID 37954478, 2023). "Dysregulation of the EGF system signaling network participates in the pathogenesis of various diseases (diabetes, autoimmune, inflammatory, cardiovascular and nervous system disorders), as well as in cancer." (PMID 37873809, 2023). "EGF regulates cancer metastasis and angiogenesis through multiple mechanisms." (PMID 36594087, 2023). "This new culture method could circumvent some weaknesses of cancer stem-like cell cultures in systems with bFGF, EGF, and B27, which are ineffective, time-consuming, and costly." (PMID 37639070, 2023). "However, how oscillatory signals mediated by chemotactic molecules CXCL12 and EGF can be targeted with novel therapies in cancer remains incompletely understood." (PMID 36829763, 2023). "Epidermal growth factor (EGF)-mediated activation of EGF receptors (EGFRs) has become an important target in drug development due to the implication of EGFR-mediated cellular signaling in cancer development." (PMID 36979595, 2023). "Additionally, overexpression of epidermal growth factor (EGF) and adrenaline receptors (Eph) promotes cancer development." (PMID 37609372, 2023). "More than 10 clinical trials have been completed with the therapeutic cancer vaccine CIMAvax-EGF, including phase II, III, and IV trials, demonstrating safety, long-term immunogenicity and a significant effect on survival, with several patients achieving long-term survival after vaccination." (PMID 37241784, 2023). "Autocrine production of EGF by cancer cells contributes to cancer cells migration and invasion." (PMID 36594087, 2023). "Since the use of nanobodies (Nbs) for EGF neutralization may be an effective therapeutic strategy in several types of cancer, in this study, we decided to generate anti-EGF Nbs from a recently constructed, phage-displaying synthetic nanobody library." (PMID 37241784, 2023). "We observed a decrease in plasma IGF-1 and EGF after surgery, varying among cancer types." (PMID 38067195, 2023). "Epidermal growth factor (EGF) stimulates ERK1/2 as well as the proliferation of carcinoma cells." (PMID 37009472, 2023). "Induced expression of AQP3 in response to EGF in colorectal, gastric, and pancreatic cancer cell lines can enhance activities leading to the aggressiveness of growing cancer cells, including increased cell migration, invasion, and metastasis with mesenchymal transformation." (PMID 35847914, 2022). "Phospholipase C (PLC) has been determined to control a range of cell functions such as cell motility, transformation, differentiation, and proliferation, and PLC also regulates cancer cells in part by serving as signaling intermediates for cytokines like EGF and interleukins." (PMID 34976314, 2022). "Furthermore, literature retrieval identified 8 out of 52 genes that were reported to be involved in the regulation of DNA repair, among which EGF was highlighted because of its role in cancer progression, and DNA repair." (PMID 35502895, 2022).
cancer (continued). "Emerging evidence revealed that EGF stimulation could trigger metabolic reprogramming in multiple types of cancer cells." (PMID 35931120, 2022). "By producing epidermal growth factor (EGF), TAMs promote cancer cell proliferation." (PMID 36341388, 2022). "Molecular inhibition of EGFR expression in cancer cells could inhibit the epidermal growth factor that induces increased proliferation, migration, and apoptosis." (PMID 34882994, 2022). "Reports indicate the use of EGF for selective uptake of nanoparticles by the cancer cells." (PMID 35778747, 2022). "Therefore, mere nuclear localization cannot fully explain the more robust effect of YAP1‐2 in promoting invasion and metastasis of cancer cells than YAP1‐1 upon EGF treatment." (PMID 35014181, 2022). "As cancer cells are exposed to a variety of mitogenic growth factors, one of our experimental strategies was to also reveal the nature of transcriptomic changes in cells stimulated with epidermal growth factor." (PMID 35892586, 2022). "EGF/EGFR activation causes the detachment of SHC-binding protein 1 (SHCBP1) from SHC adapter protein 1 (SHC1), which subsequently translocates into the nucleus and promotes cancer development via multiple signaling pathways." (PMID 35013128, 2022). "However, due to multifunctional roles of EGF in signaling pathways, it is unclear which EGF-mediated signaling pathways promote these large glucosome assemblies in cancer cells." (PMID 35122791, 2022). "Pretreatment of cancer cells with actinomycin D, a transcription inhibitor, almost abolished EGF-enhanced HIF-1α expression in GSCs, LN229, and U251 cells, suggesting that transcriptional regulation of HIF-1α is essentially involved in response to EGFR activation." (PMID 36435833, 2022). "A well-known example is the epidermal growth factor (EGF)-driven signal cascade in cancer cells." (PMID 36216834, 2022). "In most cancers, the expression of EGF was higher than normal tissues." (PMID 35655917, 2022). "Thus, our data evidence that the human blood EGF can have protective effects on cancer cells that counteract with trastuzumab cytotoxicity." (PMID 36009461, 2022). "Moreover, many cancer cells (glioblastoma, lung cancer, etc.)increase expression of EGF and other cytokine receptors, which makes the use of these radioprotectors unfeasible in cancer patients undergoing radiotherapy." (PMID 35739995, 2022). "EGF secreted by M2-like TAMs directly stimulates cancer cell proliferation and invasion." (PMID 36325334, 2022). "In addition, cancer pathways included many pathways of growth factors, such as insulin-like growth factor I, fibroblast growth factor, recombinant human epidermal growth factor, platelet-derived growth factor, and human hepatocyte growth factor." (PMID 35313857, 2022). "Furthermore, EGF severely hindered UTUC organoid establishment even though this compound was widely used to promote the growth of other cancer organoids." (PMID 34914855, 2022). "On another note, TAMs could promote cancer cell proliferation by releasing growth factors such as epidermal growth factor (EGF)." (PMID 36072957, 2022). "EGF, FGFs, and VEGFs secreted by TAMs promote cancer cell proliferation, and angiogenesis." (PMID 35847899, 2022). "However, treatment with free DOX, EGF@DOX-NPs, RT + free DOX, RT + DOX-NPs, and RT + EGF@DOX-NPs significantly decreased the proliferation of cancer cells." (PMID 35156493, 2022). "Then, EGF-responsive cancer cells were cultured with the scaffold in a dynamical bioreactor." (PMID 36015599, 2022). "Overexpression of EGF was reported in many human cancers, including HCC." (PMID 36557005, 2022). "Further, we identified the growth factors EGF and VEGF-A as potential master regulators that concordantly upregulate the expression of ECM remodeling genes encoding uPA/R and MMPs—well-recognized metastasis driver proteases in many cancer types." (PMID 35480116, 2022).